DDIT3 (DNA damage inducible transcript 3)
Diseases named in the same sentence as DDIT3 in open-access papers (continued):
Sharing a sentence is not in itself a finding about the gene and the disease.
brain hemorrhage (1 paper, 2021). "It has been shown that ATF4 increases the expression of transcriptional activator CHOP (DDIT3) and caspase-12, which promote apoptosis and reduce neuronal survival after brain hemorrhage." (PMID 34163322, 2021).
cartilage tumours (1 paper, 2024). "We further confirmed the expression of DDIT3/CHOP using eight benign and thirteen malignant cartilage tumours samples." (PMID 38267611, 2024). "Our single-cell analysis revealed ER stress regulators such as DDIT3/CHOP may be used to better differentiate benign chondroid lesion and early CCCS, providing an additional dimension for the diagnosis of malignant transformation in cartilage tumours." (PMID 38267611, 2024).
chronic graft versus host disease (1 paper, 2025). Chronic graft versus host disease (GVHD) is a complication that can occur after a stem cell or bone marrow transplant in which the newly transplanted donor cells attack the transplant recipient's body. "To investigate the impact of DDIT3 on the development of SLE, we conducted a chronic graft-versus-host disease (cGVHD) lupus-like model by transferring CD4+ T cells from Bm12 mice into WT and KO mice." (PMID 40166629, 2025).
End Stage Liver Disease (1 paper, 2020). Final stage of a liver disease when the liver failure is irreversible and LIVER TRANSPLANTATION is needed. "To confirm our in vitro data in clinical samples, we determined the mRNA expression of transcription factors ATF4 and DDIT3 in liver biopsies from patients with end-stage liver diseases." (PMID 32283772, 2020).
Fanconi anemia (1 paper, 2023). Fanconi anemia (FA) is a hereditary DNA repair disorder characterized by progressive pancytopenia with bone marrow failure, variable congenital malformations and predisposition to develop hematological or solid tumors. "These genes include DDIT3 (DNA damage-inducible transcript 3), FANCM (Fanconi anemia, complementation group M), Merlin tumor suppressor, NME1 (NME/NM23 nucleoside diphosphate kinase 1), SMAD4." (PMID 37239070, 2023).
liver dysfunction (1 paper, 2020). "While ERS gene induction was present in the two groups, DDIT3/CHOP was only upregulated in the Bil > 2 group, suggestive of a more severe ERS and/or of activation of additional detrimental signaling pathways which would add up to ERS in patients with liver dysfunction." (PMID 32407006, 2020).
lupus nephritis (1 paper, 2025). Glomerulonephritis in the context of systemic lupus erythematosus. "In addition, we also found that DDIT3 expression in lupus nephritis (LN) in the dataset GSE65391 was significantly higher than that in SLE without nephritis and HC." (PMID 40166629, 2025).
malignant lipomatous tumors (1 paper, 2015). "Using FISH, the absence of DDIT3 alteration or MDM2 amplification was indicated in the present case, thus differentiating the benign DFML from malignant lipomatous tumors." (PMID 25621027, 2015).
metastatic tumor (1 paper, 2022). "However, one was proved to be a metastatic tumor, and another was revised as DDL (case 32) which was MDM2-amplified but DDIT3-nonrearranged." (PMID 36059611, 2022).
nuclear cataract (1 paper, 2025). A cataract (disease) that involves the lens nucleus. "Thus, high levels of CRYGC5bpdup transgene expression in severely affected lenses induces UPRer and UPRmt stress responses primarily through the PERK-dependent and Atf4/Atf5/Ddit3 pathways respectively, inducing autophagy and apoptosis and thence congenital nuclear cataracts." (PMID 39994382, 2025).
nutritional disease (1 paper, 2024). "The top-scoring network for the 9h-DEGs, also consisting of ATF3, ATF6, and DDIT3, was associated with cell-to-cell signaling and interaction, nutritional disease, and organismal injury and abnormalities (score = 41)." (PMID 39466820, 2024).
teratoma (1 paper, 2020). A non-seminomatous germ cell tumor characterized by the presence of various tissues which correspond to the different germinal layers (endoderm, mesoderm, and ectoderm). "The N-benzylnonanamide JC101 induces ER stress via the protein kinase RNA-like endoplasmic reticulum kinase/ATF4/DNA damage inducible transcript 3 (DDIT3 = CHOP) pathway, which leads to the inhibition of teratoma formation." (PMID 32493501, 2020).
tumor (472 papers, 1994 to 2026). "Our study revealed that interaction of IL-26 and EphA3 in TNBC activates AKT and JNK, leading to tumor proliferation by inhibiting EGFR-TKI-provoked PERK-eIF2α-DDIT3 pathway and ER stress-associated cell death." (PMID 34021125, 2021). "C/EBP-homologous protein (CHOP; encoded by Ddit3 and also known as CHOP−10 and Gadd153) typically leads to apoptosis and correlates with tumor progression." (PMID 31417568, 2019). "Increased expression of endoplasmic reticulum stress-induced transcripts such as PPP1R15A (GADD34), heat shock proteins HSPA6 and DNAJB1, and the stress-related transcription factor DDIT3 were observed in BRAFMT tumours with the highest-risk of disease relapse." (PMID 29568398, 2018). "Furthermore, the tumor growth rate is notably reduced in DDIT3-deficient mice." (PMID 38911383, 2024). "Here, we quantified whether the cancer cell specific gene expression levels and variability of CCNE1 and DDIT3, a proapoptotic transcription factor found to be part of the stress-associated tumor cell population enriched after chemotherapy in HGSC26, are associated with patient outcomes." (PMID 35169222, 2022). "The inclusion of a stress-response factor like DDIT3 suggests a mechanism by which the tumor adapts to and survives various internal and external stresses during its growth." (PMID 41374989, 2025). "This interpretation is supported by induction of host stress- and remodeling-related genes (Ddit3, Gstp1, Spon2), representing a molecular signature of tissue repair and immune infiltration consistent with the observed tumor regression." (PMID 41463401, 2025). "ST confirmed that DDIT3 co-localizes with markers of malignancy, fibroblasts, and immune cells, highlighting its multifaceted role in tumor progression." (PMID 40867511, 2025). "It activates the intracellular tumor-suppressive stress response via upregulating the critical ER stress marker DNA damage-inducible transcript 3 (DDIT3) through the regulation of activating transcription factor 4 (ATF4)." (PMID 38568424, 2024). "Mechanistically, it has been demonstrated that upregulation of DDIT3 blunts tbx21 transcription in tumor-infiltrating CD8+ T cells, impairing T-cell effector immunity and indicating regulation of their antitumor activity." (PMID 38474084, 2024). "Integrating multi-omics data helped determine the spatial expression pattern of DDIT3 in the tumor microenvironment and its correlation with immune cell infiltration." (PMID 38911383, 2024). "The role of DDIT3 in regulating cellular stress responses and apoptosis as well as its complex interactions within the tumor microenvironment suggests it as a promising therapeutic target." (PMID 38911383, 2024). "Nonetheless, tumor cells can selectively activate DDIT3 through endogenous cellular and tumor microenvironment stressors, thereby facilitating tumor cell invasion, metastasis 12,13, angiogenesis 14, and immune evasion." (PMID 38911383, 2024). "In MLS, IL-24 expression is decreased, and knockdown of FUS::DDIT3 results in increased IL-24 expression and inhibition of tumor cell growth." (PMID 39456230, 2024). "DDIT3, a tumor suppressor protein, exerts its tumor-suppressive effects by inducing apoptosis through ER stress." (PMID 38545201, 2024). "MiR-648 is predicted to regulate 3 feature genes (DDIT3, CXCL2, and STAT3) and has been linked to inhibiting tumor development and overcoming chemotherapy resistance." (PMID 37422588, 2023). "The anti-tumor effect of ferrichrome was mediated by the upregulation of DDIT3, and superior to that of 5-FU or cisplatin." (PMID 33407519, 2021). "The anti-tumor effect of ferrichrome was mediated by the upregulation of DDIT3, and was superior to that of 5-FU or cisplatin." (PMID 33407519, 2021). "DDIT3 is an apoptosis-related tumor suppressor gene which directly promote the apoptosis of tumor cells." (PMID 33393595, 2021).
tumor (continued). "Compared with the aCtrl and bCtrl groups, the mRNA and protein expression levels of ATF4, DDIT3 and IκBα in tumour were significantly increased in all SNP‐related groups (p < 0.05), except for ATF4 protein expression in the bSNP‐50 group (p > 0.05)." (PMID 34302428, 2021). "Three genes from the PERK pathway (EIF2S1, EIF2AK3, and DDIT3) showed a positive correlation with the SCNA score across almost every tumor type." (PMID 34698427, 2021). "This suggests that the ferrichrome-induced tumor inhibition was mediated by the upregulation of DDIT3." (PMID 33407519, 2021). "This suggests that ferrichrome-induced DDIT3 targets tumor cell DNA, while 5-FU targets DNA as well as other targets, such as RNA processing." (PMID 33407519, 2021). "DDIT3 regulon is upregulated in CD44+ tumor cells, which can inhibit type I interferon (IFN-I) and IFN-stimulated gene production." (PMID 35187044, 2021). "Among them, DDIT3 which is an apoptosis-related tumor suppressor gene was found to be up-regulated with the down-regulation of FTO." (PMID 33393595, 2021). "Next, we tested the effect of pre-silencing of Ddit3 in Pmel T cells transferred into B16 tumor-bearing mice." (PMID 30894532, 2019). "DDIT3 was found to be decreased in MM-3D cells and has been reported to have tumor suppressor effects." (PMID 29914181, 2018). "The meta-analyses results indicate that in a subset of tumour types, high IMPACT expression associates with decreased expression of stress response pathways and the key ISR effector genes ATF4 and DDIT3 (CHOP)." (PMID 30466445, 2018). "The in vivo study showed that isochaihulactone suppressed tumor growth, and DDIT3 and Caspase3 overexpressed in the xenograft model, which is consistent with the in vitro study." (PMID 27852055, 2017). "To further confirm this association, we interrogated the TCGA database for SLC3A2 and DDIT3 levels in Fascin high and low tumor samples." (PMID 27819326, 2016). "DDIT3 was also viewed as a promising target in the anticancer research, for the identification of its tumor suppressor functions." (PMID 26384350, 2015). "Conversely, genes encoding proteins involved in cell growth arrest (i.e. DDIT3, MT3, SYK) are expressed in the invasive rim subpopulations of GBM specimens as compared to their matched tumor core." (PMID 23967279, 2013). "One tumor with extensive post-treatment fatty maturation was tested and found to retain the rearrangement in CHOP/DDIT3 verifying that the mature adipocytes arose from the tumor cells." (PMID 23272660, 2012). "A deeper analysis revealed upregulation of genes involved in tumor suppression (Clca2, Spink5, Igfbp6, Nptx1, Bex4, Gadd45g, Yipf5), immune regulation (IL6ra, Ccl6, Cd81, Cd244a, Cd151, and Gata4), apoptosis, and pyroptosis (Ddit3, Rgs6, and Gsdmsc2/3/4)." (PMID 39946195, 2025). "We utilized qRT-PCR to validate increased expression of various transcripts related to the IRE1α/XBP1 arm of the UPR, such as IRE1 (gene name: Ern1), Xbp1, Dnajb9, Edem1, and CHOP (gene name: Ddit3) in GA muscle of KPC tumor-bearing mice compared to control mice." (PMID 40655023, 2025). "Modulating DDIT3 activity may lead to the development of novel treatment strategies that inhibit tumor growth and metastasis." (PMID 38911383, 2024). "In addition, molecular network regulatory maps showed that apoptosis pathway-related genes (e.g., IRF7 and DDIT3) in tumor cells showed overall activation after NCAPD3 inhibition." (PMID 38711992, 2024). "Additionally, the correlations between DDIT3 expression and immune cell infiltration patterns imply its plausible role in shaping the tumor microenvironment and modulating immune responses." (PMID 38911383, 2024). "Given the proximity of the DDIT3 gene to GLI1, the use of a DDIT3 split probe may be useful in identifying the possibility of GLI1 rearrangement in neoplasms that display a phenotype or morphology typical of a neoplasm with GLI1 alteration." (PMID 38275873, 2024).
tumor (continued). "Additionally, genes associated with tumor cell apoptosis pathways showed overall activation, among which IRF7, DDIT3, and HBEGF were significantly activated." (PMID 38711992, 2024). "Although 64 primary intrathoracic MLs have been reported, only one tumor was DDIT3-rearranged." (PMID 36059611, 2022). "In addition, it has been shown that tumor growth is heavily dependent on glutamine and that glutamine deprivation increases DDIT3 expression through activating transcription factor-4 (ATF4)-mediated transcription." (PMID 36233241, 2022). "DDIT3 was an apoptosis-related tumor suppressor gene downstream of mTORC1 signaling." (PMID 33393595, 2021). "Based on these, it was speculated omeprazole induced FTO inhibition could increase the transcript level of DDIT3, which is an apoptosis-related tumor suppressor gene downstream of mTORC1 signaling through an m6A-dependent mechanism." (PMID 33393595, 2021). "Recently, we have shown that Dox promoted UPR-related apoptotic protein CCAAT/enhancer-binding homologous protein (CHOP)/DNA damage-inducible transcript 3 (DDIT3) in normal as well as in hearts from tumor-bearing animals which was dependent on Bax—a mitochondrial proapoptotic protein." (PMID 34943000, 2021). "Furthermore, higher expression levels of ATF3, PPP1R15A, PPP2R5B, DDIT3, and BCL10 are associated with better prognosis in HER2+-BC patients, suggesting an overall tumor-suppressive role of the UPR-driven signaling cascade." (PMID 34007022, 2021). "It is speculated that the promoter regions of DDIT3 may be modulated through genetic or epigenetic modification in A2 and C9 organoids, resulting in a low tumor-suppressive effect despite the significant induction of DDIT3 when treated with ferrichrome." (PMID 33407519, 2021). "Meanwhile, omeprazole induced FTO inhibition could increase the transcript level of DDIT3, which is an apoptosis-related tumor suppressor gene downstream of mTORC1 signaling through an m6A-dependent mechanism." (PMID 33393595, 2021). "Noteworthy, compared to their healthy counterparts, tumor infiltrating MDSCs exhibit higher levels of DNA damage inducible transcript 3 (DDIT3; also known as CHOP), a proapoptotic transcription factor downstream of PERK branch that is key for MDSC turnover and immunosuppressive function." (PMID 31535086, 2019). "Thus Ddit3 mRNA levels were assessed in CD8+ T cells sorted from the spleens of tumor-free mice or tumors and spleens of mice bearing subcutaneous (s.c.)3LL, EL-4, MCA-38, or B16 cancer cells." (PMID 30894532, 2019). "In our study, however, inhibition of DDIT3 expression by shRNA effectively restored ERα expression and reversed miR-1271-deficiency impaired letrozole-sensitivity in MCF7 cells, suggestive of an opposite tumor promoting effect." (PMID 29291017, 2017). "Finally, K8 reduced the tumor size considerably, and increased DDIT3 and caspase-3 expression in vivo." (PMID 27852055, 2017). "Tumor histology and the presence of the DDIT3 gene were examined using samples from P1, P3, and P5." (PMID 28903344, 2017). "The induction of DNA-damage inducible transcript 3 (Ddit3), a transcription factor for expression of DNA repair genes, might be an adaptive response to programmed cell death in tumour cells." (PMID 21152443, 2010). "Therefore, in PCa, the DDIT3-SPOP axis significantly influences tumor growth and progression." (PMID 40521202, 2025). "In addition, HDAC8 expression was positively correlated with the genes encoding T‐cell exhaustion‐related genes, including TOX and DDIT3, and negatively correlated with the transcript genes encoding T‐cell activation‐related genes, such as TBX21, in multiple tumor types." (PMID 40013761, 2025).
tumor (continued). "Besides the involvement of DDIT3 in apoptotic and autophagic cell death, it has been demonstrated that this transcription factor can activate inflammatory responses that generally sustain tumor progression." (PMID 34371724, 2021). "Thus, the drastic upregulation of DDIT3 induced by anti-IMD antibodies may be responsible for the inhibitory effects of anti-IMD antibodies on HCC tumor growth." (PMID 33436794, 2021). "Therefore, we also analyze that the correlation of linc00423 and DDIT3 results showed that linc00423 had a positive correlation with DDIT3, suggesting that linc00423 may be a tumor-suppressor gene in RLS (P < 0.0001)." (PMID 31160581, 2019). "L. casei produces ferricrome, which triggers apoptosis in tumor cells by activating the c-Jun N-terminal kinase (JNK) pathway and subsequently induces DNA damage-inducible transcript 3 (DDIT3) exprssion in cancer cells." (PMID 41486167, 2026). "•DDIT3 regulates ECM remodeling and growth factor secretion in fibroblasts, supporting tumor growth.•CAFs modulate immunosuppression through ECM remodeling." (PMID 40867511, 2025). "This pathway downregulates DNA damage-inducible transcript 3 (DDIT3) at the protein level, contributing to anti-apoptotic signaling and enhanced tumor progression." (PMID 41516201, 2025). "•High DDIT3 expression reduces naïve B cells, promoting an immunosuppressive TME.•Plasma cells are more abundant in tumor-cell-enriched regions." (PMID 40867511, 2025). "Specifically, this tumor is driven by the translocation of DDIT3 (DNA damage-inducible transcript 3, also known as C/EBP-homologous protein/CHOP)." (PMID 39330026, 2024). "In MLS, FUS::DDIT3 can induce PAI-1 expression by inhibiting miR-486 expression, thus promoting tumor metastasis." (PMID 39456230, 2024). "Hence, the exact molecular mechanism of FUS::DDIT3 in tumor cell transformation remains unclear." (PMID 38671504, 2024). "For instance, tumor sample CCGA-UBC-034T contained an ecDNA with seven genes, including CDK4, DDIT3, GLI1, HMGA2, PTPN11, RFC5, and TMPO." (PMID 39267784, 2024). "A distinct feature of our series is the examination of the tumor samples, not only for histological diagnosis but also for the presence of the pathognomonic gene translocation FUS::DDIT3 or EWSR1::DDIT3." (PMID 36907960, 2023). "Immunohistochemical analyses of harvested tumours confirmed downregulation of NCP26 targets, including MYC, CCND1 and TCF3, and ISR engagement, evidenced by induction of p-GCN2 and DDIT3." (PMID 36631435, 2023). "Peri-necrotic and palisading tumor regions also exhibited elevated expression of hypoxia-response genes such as HILPDA, LDHA, ENO2, and DDIT3 relative to other regions." (PMID 35973991, 2022). "The WWTR1–ASNS network, ATF4–ASNS network, and DDIT3–ASNS network are reported to inhibit the proliferation and tumor formation of cancer cells." (PMID 35625787, 2022). "In some anti-tumor cell experiments, certain compounds can upregulate ERS markers, including DDIT3, and induce cytoplasmic vacuolation and the cell death." (PMID 35464062, 2022). "Quantitative real‐time PCR confirmed up‐regulation of DDIT3 (CHOP), HSPA5 (BIP), and PPP1R15A (GADD34) transcripts belonging to PERK pathway in ERO1 KO MDAMB231* tumours." (PMID 35853086, 2022). "As shown in the volcano plot, SU decreased GZMB expression and upregulated genes related to inflammatory activation (FOS, JUN, NFKBIA, DUSP2, JAK1, PIM1), tumor immunity (CD47, PCBP2, EIF5A, PDIA3, EGR1), and DNA damage (H2AFX, DDIT3, GADD45B)." (PMID 34824394, 2021).